ENG (endoglin)
Diseases named in the same sentence as ENG in open-access papers (continued):
Sharing a sentence is not in itself a finding about the gene and the disease.
preeclampsia (continued). "Previous studies showed that women with preeclampsia had persistent elevated placental HIF-1α levels that enhanced the transcription of genes that encoded soluble fms-like tyrosine kinase-1 (sFlt-1), soluble endoglin (sEng), and endothelin-1 (ET-1), all known to contribute to preeclampsia." (PMID 33758274, 2021). "In addition to the membrane-bound protein, high levels of circulating endoglin (soluble endoglin; sEng) in plasma from patients with preeclampsia, cancer, or inflammatory-related diseases such as atherosclerosis, psoriasis, or rheumatoid arthritis, has been reported." (PMID 31242676, 2019). "•Endoglin pathway genetic variation in preeclampsia may vary by ancestry." (PMID 29580923, 2018). "In summary, we describe here a novel role of endoglin and its soluble form (SolEng) in cellular adhesion involving mural cells/podocytes that may help to better understand the function of endoglin in angiogenesis as well as in several pathophysiological processes, such as preeclampsia or HHT1." (PMID 26646071, 2016). "Previous studies found that antiangiogenic factors such as soluble fms-like tyrosine kinase 1 (sFlt1; also known as soluble vascular endothelial growth factor receptor-1) and soluble endoglin (sEng) levels may play an important role in the pathogenesis of preeclampsia." (PMID 26498356, 2015). "Several studies have suggested that the main features of preeclampsia (PE) are consequences of endothelial dysfunction related to excess circulating anti-angiogenic factors, most notably, soluble sVEGFR-1 (also known as sFlt-1) and soluble endoglin (sEng), as well as to decreased PlGF." (PMID 22428059, 2012). "Most probably, this effect could be attributed to the inhibitory effect of Sol-endoglin on TGF-β1-mediated eNOS activation in ECs, and it has been suggested that high levels of circulating Sol-endoglin could contribute to the hypertension shown by women with preeclampsia." (PMID 21171985, 2010). "AT1-AA is one of several mediators of hypertension during pregnancy, along with increasing soluble fms-like tyrosine kinase-1 (sFlt1) and soluble endoglin (CD105) (sEng), and endothelin-1, which are elevated in women with preeclampsia." (PMID 40904461, 2025). "In preterm preeclampsia, PlGF and VEGFR-1 displayed a differential abundance in both soluble and EV fractions, whereas angiogenin, CD40L, endoglin, galectin-1, and TIMP1 were changed only in the soluble fraction." (PMID 41515555, 2025). "Among these, endoglin (CD105), a glycoprotein in elevated levels in the blood plasma of women with preeclampsia, has emerged as a particularly promising target." (PMID 39727876, 2024). "Exercise increases apelin levels to reduce preeclampsia symptoms by increasing eNOS, NO, placental growth factor (PlGF), and VEGF and decreasing levels of fms-like tyrosine kinase 1 (sFlt-1), soluble endoglin (sEng), and oxidative stress." (PMID 37964253, 2023). "In fact, soluble FLT1 and ENG antagonizes VEGF binding to its receptor contributing to hypertension, proteinuria and endothelial cell dysfunction in preeclampsia." (PMID 35943095, 2022). "Thus, key manifestations of preeclampsia, i.e., maternal hypertension, fetal growth restriction, and/or maternal vascular endothelial dysfunction, were induced in mice or rats in which levels of sFlt1 and/or endoglin were elevated by systemic adenoviral delivery of these proteins." (PMID 32548805, 2020). "The production of soluble Endoglin/CD105 by the membrane metalloproteinase-14 induces the squelching of TGF-β1, endothelial dysfunction, and impaired relaxation, altogether, preeclampsia." (PMID 30044452, 2018). "To investigate this, we first assessed the expression of the two most frequently studied markers of preeclampsia, soluble FLT1 (sFLT1) and soluble ENG (sENG), produced in the placenta and found elevated in the maternal serum early in pregnancy." (PMID 25679511, 2015).
preeclampsia (continued). "On the other hand, Calretinin, HtrA, Flt-1, Nox4 and Endoglin were positively and Annexin XI and PLGF were inversely correlated with the severity of term preeclampsia." (PMID 25392996, 2014). "Elevations in circulating soluble endoglin (sENG) and placental/blood ENG mRNA expression antedate the clinical onset of preeclampsia." (PMID 23548068, 2013). "Soluble endoglin (sENG), which is released into circulation after cleavage of trans-membrane ENG by matrix metalloproteinase-14 (MMP-14), is also elevated in preeclampsia." (PMID 23548068, 2013). "From these 18 microarray studies in preeclampsia, the most repeatedly reported genes are fms-like tyrosine kinase 1 (FLT1) and endoglin (ENG)." (PMID 22929622, 2012). "Endoglin is classified as a type III TGF-β receptor, playing a crucial role in angiogenesis, preeclampsia and cancer." (PMID 22347366, 2012). "Endoglin is widely involved in the regulation of inflammation in various immune diseases, including rheumatic diseases, hereditary hemorrhagic telangiectasia-1 (HHT-1), and preeclampsia." (PMID 41030313, 2025). "Interestingly, the contribution of sENG to vascular pathology in preeclampsia is partially due to effects on NOS3; in concert with FLT1, ENG reduces placental angiogenesis and vasodilation of maternal spiral arteries, and increases vessel permeability." (PMID 37012406, 2023). "At a functional level, preeclampsia‐derived EVs, but not normal pregnancy EVs, showed an antiangiogenic effect, possibly due to the decoy effect of endoglin." (PMID 35582873, 2022). "Soluble endoglin levels also were significantly higher in the women with preeclampsia (P = 0.002; area under the curve, 0.77, not shown)." (PMID 29803833, 2018). "Thus, a dysregulation of pro and anti angiogenic factors has been described which contributes significantly to the pathogenesis of preeclampsia, among these VEGF, sFlt-1, PlGF, endothelin, and endoglin." (PMID 26121675, 2015). "FLT1, LEP, INHA and ENG genes were identified according to the literature, however, we also found other genes as FLNB, INHBA, NDRG1 and LYN highly significant but underexplored during normal pregnancy or preeclampsia." (PMID 24219996, 2013). "We conclude MMP-15 is up-regulated in preeclampsia, but does not cleave endoglin to produce soluble endoglin." (PMID 22768148, 2012). "A Korean study demonstrated that the combined ratio of (sFlt-1 + soluble endoglin) : (PGF + TGF beta −1) during the second trimester had the highest odds ratio and lowest false positive rate as compared to the individual markers for prediction of preeclampsia." (PMID 22685661, 2012). "This find identifies a specific drug target for severe preeclampsia; interfering with MMP-14 mediated cleavage of endoglin could decrease soluble endoglin production, ameliorating clinical disease." (PMID 22768148, 2012). "Preeclampsia is attributed to an imbalance of placental-derived circulating pro-angiogenic (vascular endothelial growth factor, VEGF; placental growth factor, PlGF; membrane-bound endoglin, ENG) and anti-angiogenic (soluble fms-like tyrosine kinase 1, sFLT1; soluble endoglin, sENG) factors." (PMID 41416997, 2025). "Indeed, it was demonstrated that human sEng affected mouse endoglin signaling and aggravated mice aortic endothelial dysfunction, mice cholesterol and BA metabolism, mice NASH and induced symptoms of preeclampsia in mice." (PMID 36778021, 2023). "Finally, to quantify the attenuation of differential expression of the preeclampsia biomarkers FLT1, LEP, and ENG, we applied mediation analysis to show cellular composition mediated a substantial proportion of the association between preeclampsia and FLT1, LEP, and ENG overexpression." (PMID 36914823, 2023). "Interestingly, a detailed characterization of plasma from women with preeclampsia has revealed that circulating endoglin can be complexed within exosomes, rather than as individual soluble endoglin." (PMID 30761306, 2019).
preeclampsia (continued). "It is recognized that in mature ECs, ENG plays a key role in angiogenesis and blood vessel homeostasis, becoming a potential therapeutic target for pro- and anti-angiogenic approaches in the treatment of diseases such as HHT, cancer, preeclampsia, diabetes complications or post-ischemic disease." (PMID 30761306, 2019). "The roles of other molecules generated by shallow placentation and/or reduced uteroplacental perfusion, such as anti-angiogenic factors, soluble fms-like tyrosine kinase-1 (sFlt-1) and soluble endoglin (sEng) and endoglin, in the pathogenesis of preeclampsia are not discussed." (PMID 31551925, 2019). "•The endoglin pathway’s role in preeclampsia has not been fully elucidated." (PMID 29580923, 2018). "However, the fact that both parameters are elevated in preeclampsia does not demonstrate that soluble endoglin induce inflammation." (PMID 29145462, 2017). "We do not know how the inflammation in preeclampsia would be in the absence of soluble endoglin, it might be that we would found a greater inflammation than that observed with elevated levels of circulating endoglin." (PMID 29145462, 2017).
breast carcinoma (88 papers, 2003 to 2026). "In this study, we demonstrated that stronger ENG staining in myCAFs in tumor stroma is associated with a poorer outcome in breast cancer patients, and that ENG expression is progressively upregulated on human breast CAFs during tumor progression." (PMID 40644310, 2025). "ROC Plotter analysis revealed decreased ENG expression to be associated with response to anthracycline therapy in Luminal A breast cancer patients." (PMID 33819300, 2021). "On the other hand, a study involving HHT patients, relatives, and controls showed that endoglin deficiency reduces the incidence of solid tumors, especially breast cancer." (PMID 33800564, 2021). "In gastric and breast cancer, a strong association between endoglin-expressing CAFs/MSCs and a poor prognosis was reported." (PMID 32059544, 2020). "Since HHT patients with endoglin mutations express approximately half normal endoglin, there would therefore be even more reason to predict that breast cancer rates should be higher in HHT patients." (PMID 24354965, 2013). "In the current study, we evaluated ENG/CD105 expression, DNA methylation, immune response, and CD regulation, which could act as diagnostic, prognostic, and therapeutic markers of breast cancer (BC) including BRCA." (PMID 39247590, 2024). "Similarly, several independent research groups reported an association of plasma endoglin with distant metastasis in patients with both colorectal and breast cancers." (PMID 34587660, 2022). "In keeping with these data, ENG targeting using the TRC105 anti-ENG antibody or an ENG ligand trap (ENG-Fc) significantly dampened metastatic spread in breast cancer mouse models, which was associated with a strong reduction in the CAF content of primary tumors." (PMID 33804796, 2021). "However, a previous study showed that positive ENG expression was associated with increased survival in breast cancer patients who had undergone anthracycline treatment." (PMID 33819300, 2021). "The role of Sol-ENG in cancer is therefore controversial, since it seems to be involved in the inhibition of tumor-associated angiogenesis but also in activities that promote a malignant phenotype in myeloma and breast cancer cells." (PMID 33804796, 2021). "Hence, sEV‐associated Endoglin might be a target for the Integrins of migrating breast cancer cells, concomitantly supporting epithelial detachment as a competitive inhibitor of intercellular junctions." (PMID 40831280, 2025). "In breast cancer, these elevated endoglin levels are correlated with reduced survival and invasive phenotype." (PMID 41532547, 2026). "To more precisely evaluate ENG staining on stromal fibroblasts and better determine the clinical significance, we employed a larger cohort including 232 breast cancer patients and performed immunohistochemistry with an anti‐ENG antibody." (PMID 40644310, 2025). "We observed an absence of ENG staining in both intralobular and interlobular areas of the noncancerous breast tissue, indicating that increased ENG staining is mainly on CAFs in human breast cancer samples of our cohort." (PMID 40644310, 2025). "We observed intense ENG staining on stromal fibroblast‐like cells on tumor sections from two (estrogen receptor‐positive) of the 33 breast cancer patients." (PMID 40644310, 2025). "Herein, we show that the abundance of endoglin (ENG), a TGF‐β superfamily coreceptor expressed on human breast myCAFs, is significantly associated with poorer outcomes of breast cancer patients." (PMID 40644310, 2025). "We identified endoglin (ENG) as a key factor in TGF‐β signaling in myofibroblastic CAFs (myCAFs), linked to poor breast cancer outcomes." (PMID 40644310, 2025). "Endoglin depletion has been shown to reduce cancer-promoting pathways, including TGF-β/SMAD3/VEGF and MAPK/p38 signaling, induced by breast cancer-causing phthalates." (PMID 40072060, 2025).
breast carcinoma (continued). "Inhibition of ENG expression in CAFs also attenuated their ability to promote lung metastasis spontaneously formed by breast cancer cells." (PMID 40644310, 2025). "To address how the inhibited ENG expression in CAFs contributed to the attenuated mammary carcinoma growth, we prepared sections from different tumors and performed Azan‐Mallory staining for collagen fibers." (PMID 40644310, 2025). "Similar results were observed when anti-endoglin monoclonal antibodies were used to treat metastasis models of mammary carcinoma." (PMID 38761292, 2024). "Inhibition of ENG has been shown to prevent tumor angiogenesis and metastatic spread in human breast cancer." (PMID 38951817, 2024). "High expressions of ENG remarkably correlate with long relapse-free survival (RFS) for breast cancer (BC)." (PMID 39247590, 2024). "In relation to this, it has been found that 90%–95% of human bone marrow-MSCs express CD105 (endoglin) as well as 50% of CAFs in the tumor stroma of breast cancer patients (BCPs) express CD105." (PMID 37719885, 2023). "In preclinical murine xenograft models of HR(+) breast cancer, anti-endoglin monoclonal antibodies selectively inhibited tumor angiogenesis and delayed the growth of established tumors, while sparing normal vasculature." (PMID 36735117, 2023). "For example, tenascin C induces EMT in breast cancer cells, endoglin regulates EMT in renal cell carcinoma, carbonic anhydrase IX promotes EMT in prostate cancer cells, and osteopontin has been credited as a master regulator of EMT." (PMID 36012449, 2022). "In murine mammary carcinoma, endoglin silencing reduces the growth and number of vessels formed during tumor progression." (PMID 35203627, 2022). "Solid tumors such as prostate, cervical, and breast cancer showed an increased level of endoglin in the endothelium." (PMID 35203627, 2022). "INHA, INHBA, TGFBR3, and ENG also predicted patients’ response to anthracycline and taxane therapy in luminal A breast cancers." (PMID 33819300, 2021). "We next examined individual genes and find that in luminal A breast cancers ENG, TGFBR3, INHA, and INHBA, were better performing as compared to INHBB particularly for taxane or anthracycline based chemotherapy regimens." (PMID 33819300, 2021). "ENG was also more expressed in HER2+ breast cancer patients who respond to taxane therapy, which was opposite to the luminal A subtype expression levels." (PMID 33819300, 2021). "In summary INHA, INHBA, TGFBR3, and ENG display clear discrepant profiles of expression among responders and non-responders to both anthracycline and taxane chemotherapy for distinct breast cancer subtypes, specifically luminal A, and serous ovarian cancer." (PMID 33819300, 2021). "Treatment with drug conjugates of Sn6j or other endoglin antibodies showed long-lasting tumor remission of human breast cancer xenografts and the inhibition of tumor angiogenesis in vivo." (PMID 33375670, 2020). "Single-cell RNA sequencing studies on breast cancer have identified a subpopulation of so-called vascular CAFs (vCAFs), which are characterized by their expression of endoglin." (PMID 32059544, 2020). "In breast cancer, endoglin expression has been investigated in a subset of invasive breast cancer cell lines." (PMID 32059544, 2020). "Similar findings had been previously achieved by Salgado and co-workers, who had also investigated endoglin expression in the vessels of BM and had found less intense angiogenesis in BM from melanoma in comparison to those from lung and breast cancer." (PMID 24699047, 2014). "Anti-tumor effectiveness and anti-metastatic activity of naked anti-endoglin antibodies were also reported in immunocompetent BALB/c mice bearing 4T1 mammary carcinoma or colon-26 colon carcinoma." (PMID 23593103, 2013). "Interactions of the breast cancer cells with integrins, fibronectin, tenascin C, laminins, collagens, endoglin, hyaluronan, heparanase and proteoglycans can contribute to the metastatic process." (PMID 23343205, 2013).